SCGB1C1 (secretoglobin family 1C member 1)
Synonyms: RYD5
Tractability: Antibody: UniProt places it where antibodies can reach, with medium confidence; UniProt predicts a signal peptide or a membrane-spanning region; its Gene Ontology location is reachable by antibodies, with medium confidence.
Gene: Protein-coding gene on chromosome 11 (193,078 to 194,575, forward strand). Ensembl gene ENSG00000188076.
Subcellular location: Secreted
Gene Ontology:
Cellular component: extracellular region
Genetic constraint (gnomAD): Loss-of-function variants: 1 observed, 3.65 expected, observed/expected ratio (o/e) 0.27, 90% interval 0.096 to 1.26. That is too few expected variants to judge how well the gene tolerates losing a copy. Missense variants: 18 observed, 55.24 expected, observed/expected ratio (o/e) 0.33, 90% interval 0.22 to 0.48. Synonymous variants: 6 observed, 19.74 expected, observed/expected ratio (o/e) 0.3, 90% interval 0.17 to 0.6.
Homologues: Orthologues: macaque SCGB1C1 (94% identical), dog SCGB1C1 (80% identical), guinea pig Scgb1c1 (77% identical), rat Scgb1c1 (75% identical), mouse Scgb1c1 (72% identical). Paralogues in human: SCGB1C2 (99% identical), SCGB1A1 (27% identical).
Diseases named in the same sentence as SCGB1C1 in open-access papers:
SCGB1C1 is named in the same sentence as 6 diseases in open-access papers, as found by Europe PMC text mining. Sharing a sentence is not in itself a finding about the gene and the disease.
SCGB1C1 shares sentences with these, for which no sentence is quoted: allergic rhinitis (1 paper); Allergy (1); asthma (1); breast carcinoma (1); ovarian carcinoma (1); squamous cell carcinomas of the (1).